LRRC58 (leucine rich repeat containing 58)
Description:
Substrate-recognition component of a cullin-5-RING E3 ubiquitin-protein ligase complex (ECS complex, also named CRL5 complex), which mediates the ubiquitination and subsequent proteasomal degradation of target proteins, such as CDO1. The ECS(LRRC58) complex acts as a regulator of cysteine catabolism by mediating ubiquitination and degradation of CDO1, the rate-limiting enzyme of the cysteine catabolic process to taurine. L-cysteine abundance regulates ECS(LRRC58)-mediated ubiquitination of CDO1: the complex promotes ubiquitination and degradation of CDO1 in presence of high level of cysteine, but not when cysteine abundance is low.
Tractability: PROTAC: ubiquitination databases record sites on it; its protein half-life has been measured.
Gene: Protein-coding gene on chromosome 3 (120,324,509 to 120,349,409, reverse strand). Ensembl gene ENSG00000163428.
Subcellular location (Human Protein Atlas): Nucleoplasm; Cytosol
Gene Ontology:
Molecular function: ubiquitin-like ligase-substrate adaptor activity
Biological process: proteasome-mediated ubiquitin-dependent protein catabolic process; regulation of taurine biosynthetic process; intracellular signal transduction
Cellular component: Cul5-RING ubiquitin ligase complex
Genetic constraint (gnomAD): Loss-of-function variants: 13 observed, 19.16 expected, observed/expected ratio (o/e) 0.68, 90% interval 0.44 to 1.08. The synonymous counts are far from expectation, so gnomAD's model fits this gene poorly and the ratio says little. Missense variants: 383 observed, 361.52 expected, observed/expected ratio (o/e) 1.06, 90% interval 0.97 to 1.15. Synonymous variants: 205 observed, 159.94 expected, observed/expected ratio (o/e) 1.28, 90% interval 1.14 to 1.44.
Homologues: Orthologues: chimpanzee LRRC58 (99% identical), macaque LRRC58 (99% identical), rabbit LRRC58 (96% identical), pig LRRC58 (96% identical), dog LRRC58 (94% identical), rat Lrrc58 (94% identical), mouse Lrrc58 (93% identical), guinea pig LRRC58 (86% identical), tropical clawed frog lrrc58 (66% identical), zebrafish lrrc58b (58% identical), zebrafish lrrc58a (54% identical), Drosophila melanogaster CG32687 (46% identical), and 1 more. Paralogues in human: LRRC40 (27% identical), ERBIN (26% identical), SCRIB (26% identical), LRRC7 (25% identical), LRRC1 (25% identical), LRRD1 (25% identical), MFHAS1 (25% identical), PIDD1 (24% identical), PHLPP1 (24% identical), PHLPP2 (23% identical), LRRIQ4 (22% identical), SHOC2 (21% identical), and 19 more.
Diseases named in the same sentence as LRRC58 in open-access papers:
LRRC58 is named in the same sentence as 3 diseases in open-access papers, as found by Europe PMC text mining. Sharing a sentence is not in itself a finding about the gene and the disease. The quoted sentences say what the papers report.
cancer (1 paper, 2015). A tumor composed of atypical neoplastic, often pleomorphic cells that invade other tissues. "Six of fifty genes were not previously known to associate with cancer (HMGB1L5, LRRC58, GPR149, DZIP1L, C3orf77, and NUDT16)." (PMID 26491211, 2015).
LRRC58 also shares sentences with these, for which no sentence is quoted: prostate carcinoma (1 paper); prostate tumors (1).